REXO4 (RNA exonuclease 4)
Synonyms: hPMC2; XPMC2H; REX4; XPMC2
Tractability: PROTAC: UniProt records ubiquitination sites on it; ubiquitination databases record sites on it; its protein half-life has been measured.
Gene: Protein-coding gene on chromosome 9 (133,406,059 to 133,418,096, reverse strand). Ensembl gene ENSG00000148300.
Subcellular location: Nucleus, nucleolus
Subcellular location (Human Protein Atlas): Nucleoli; Nucleoplasm
Gene Ontology:
Molecular function: 3'-5' exonuclease activity; double-stranded DNA binding; endonuclease activity; protein binding; RNA binding; single-stranded DNA binding; exonuclease activity; nucleic acid binding
Biological process: DNA catabolic process; DNA repair; regulation of DNA-templated transcription; RNA processing; rRNA processing
Cellular component: nucleolus; nucleoplasm; nucleus
Genetic constraint (gnomAD): Loss-of-function variants: 25 observed, 36.91 expected, observed/expected ratio (o/e) 0.68, 90% interval 0.49 to 0.95. The upper end of that interval is the gene's LOEUF score, 0.95, which puts it in group 4 of 6, group 1 being the genes least tolerant of losing a copy. Missense variants: 497 observed, 534.33 expected, observed/expected ratio (o/e) 0.93, 90% interval 0.86 to 1. Synonymous variants: 174 observed, 202.66 expected, observed/expected ratio (o/e) 0.86, 90% interval 0.76 to 0.97.
Homologues: Orthologues: chimpanzee REXO4 (99% identical), macaque REXO4 (94% identical), guinea pig REXO4 (71% identical), dog REXO4 (70% identical), mouse Rexo4 (68% identical), pig REXO4 (68% identical), rat Rexo4 (67% identical), zebrafish rexo4 (43% identical), Drosophila melanogaster CG6833 (25% identical). Paralogues in human: REXO1 (22% identical), AEN (22% identical), ISG20L2 (22% identical), REXO5 (15% identical), ISG20 (15% identical).
Diseases named in the same sentence as REXO4 in open-access papers:
REXO4 is named in the same sentence as 8 diseases in open-access papers, as found by Europe PMC text mining. Sharing a sentence is not in itself a finding about the gene and the disease. The quoted sentences say what the papers report.
breast carcinoma (2 papers, 2023 to 2024). "The downregulation of REXO4 in breast cancer MDA-MB-231 cells resulted in improved sensitivity of temozolomide by increasing the number of apurinic/apyrimidinic sites in the DNA and the enhancement of DNA double strand breaks." (PMID 37913903, 2024).
familial isolated pituitary adenoma (1 paper, 2024). "Previous studies indicated that REXO4 was involved in neuropathic pain and familial isolated pituitary adenoma (FIPA)." (PMID 37913903, 2024).
hepatocellular carcinoma (1 paper, 2024). A malignant tumor that arises from hepatocytes. "The proliferation and progression of hepatocellular carcinoma (HCC) could be inhibited by the downregulation of REXO4." (PMID 37913903, 2024). "Inspired by the result that downregulation of REXO4 protein in hepatocellular carcinoma (HCC) was beneficial to the cell multiplication inhibition, we hypothesized that the interaction with REXO4 might be helpful for the proliferation inhibition of HCT116 cells." (PMID 37913903, 2024).
liver cancer (1 paper, 2024). An epithelial or non-epithelial malignant neoplasm that arises from the liver. "In addition, a clinical study indicated that the REXO4 expression level could act as a biomarker for targeted therapeutic regimens and predictor for the prognosis of liver cancer." (PMID 37913903, 2024).
cancer (1 paper, 2022). A tumor composed of atypical neoplastic, often pleomorphic cells that invade other tissues. "Unlike KDM5B, REXO4 is much less well-investigated in cancer biology." (PMID 35954332, 2022).
tumor (1 paper, 2024). "Also, the designed EVO-PROTACs provide valuable tools for better understanding the role of REXO4 in tumor." (PMID 37913903, 2024).
REXO4 also shares sentences with these, for which no sentence is quoted: infection (1 paper); uveal melanoma (1).